EZR (ezrin)
Diseases named in the same sentence as EZR in open-access papers (continued):
Sharing a sentence is not in itself a finding about the gene and the disease.
prostate carcinoma (24 papers, 2010 to 2024). A carcinoma that arises from epithelial cells of the prostate gland. "More clinical research and data collection should also be performed in the future to prove the diagnostic value of Ezrin in prostate cancer." (PMID 35156523, 2022). "The knockdown of ezrin had a profound effect on DU145 prostate cancer cells, inducing morphological changes and the appearance of EV-like structures at the cell surface." (PMID 39858418, 2024). "Using androgen-insensitive DU145 prostate cancer cells, which have higher endogenous ezrin expression, we knocked down ezrin and observed cells under SEM to investigate the effect on TNT and EV morphology." (PMID 39858418, 2024). "Subsequently, we adopted three human prostate cancer cell lines, 22RV1 and PC-3, to further detect Ezrin expression." (PMID 35156523, 2022). "Podocalyxin (including PODXL1, PODXL2 and PODXL3) induction resulted in altered migration and invasion, increased MMP expression with increased MAPK and PI3K activity through forming a complex with Ezrin protein, in breast and prostate cancer." (PMID 32998690, 2020). "In the non-type molecular subtype, TLN1 is significantly hyperphosphorylated at S425 in the head domain (band 4.1, ezrin, radixin, moesin homology domain), a site also known to be hyperphosphorylated in prostate cancer." (PMID 31108958, 2019). "In high grade prostate cancers, overexpression of ezrin has been reported, and this was attributed to increased expression of oncogenic c-Myc." (PMID 26983550, 2016). "Gene ontology analysis of differentially expressed genes revealed that lack of Sost in the bone microenvironment up-regulated several genes associated with the GO term “chemotaxis” including MET, PDGFA, FER, NRP2, and EZR in prostate cancer." (PMID 27600237, 2015). "Phosphorylation of ezrin at Y353 was found to be mediated through Src tyrosine kinase in prostate cancer, and it is a crucial element of Src-induced features in malignant cells." (PMID 25866790, 2015). "In parallel, it has been reported that ezrin phosphorylation is required for androgen-induced prostate cancer cell invasion." (PMID 21818323, 2011). "It showed that sex steroid androgen indirectly phosphorylates ezrin at Thr567 via PKC pathway and directly phosphorylates Tyr353 via c-Src, leading to ezrin full activation and promoting prostate cancer cell invasion." (PMID 21818323, 2011). "Ezrin has been shown to mediate invasion of prostate cancer cells, but whether it is overexpressed in prostate cancer is not known." (PMID 20860828, 2010). "Indeed, ezrin and other actin binding proteins have increased expression in prostate cancer and may play a critical role in linking membrane to cytoskeletal microfilaments and TNT formation." (PMID 39858418, 2024). "Moreover, the mRNA expression of Ezrin was highest in the prostate cancer-B group." (PMID 35156523, 2022). "This hypothesis is further supported by the previously demonstrated ability of PODXL to form complex with ezrin in breast and prostate cancer cells in vitro, thereby inducing phosphorylation of ezrin and changes in its subcellular location, in turn leading to an increased migration and invasion." (PMID 24885195, 2014). "Similar effects of Uba6 knockdown on cellular levels of ezrin and CUGBP1 were observed in human prostate epithelial RWPE-1 cells and prostate carcinoma PC3M cells." (PMID 28134249, 2017). "Here we report a novel interaction of ezrin with a HECT E3 ubiquitin ligase, WWP1/Aip5/Tiul1, a potential oncogene that undergoes genomic amplification and overexpression in human breast and prostate cancers." (PMID 22629406, 2012). "Intracellularly, podocalyxin has been found to form complexes with ezrin and to influence the activities of Rac1, MAPK, and PI3K, increasing the metastatic potential of breast, kidney and prostate cancers." (PMID 21533279, 2011).
prostate carcinoma (continued). "In contrast to previous reports, we showed that ezrin had reduced expression in prostate cancer cells compared to non-malignant cells, albeit with variable expression between different prostate cancer cell lines." (PMID 39858418, 2024). "Ezrin and moesin expression was reduced in androgen-sensitive LNCaP and 22Rv1 prostate cancer cell lines compared to androgen-sensitive non-malignant PWR-1E prostate cells." (PMID 39858418, 2024). "The results showed that the mRNA expression of Ezrin was significantly increased in the prostate cancer-lymph node metastasis (PCa-L) and the prostate cancer-bone metastasis (PCa-B) groups compared with the prostate cancer group." (PMID 35156523, 2022). "The survival rate in prostate cancer patients with high expression or low expression of Ezrin was not followed." (PMID 35156523, 2022). "Ezrin also participates in the activation of MAPK and PI3K in both breast and prostate cancers." (PMID 26933912, 2016). "Ezrin also participates in the activation of MAPK and PI3K in breast and prostate cancer." (PMID 23357878, 2013). "The other members of the 4.1 family had not been studied yet in prostate cancer, but previous investigations have indicated potential functions for the related proteins ezrin and dematin." (PMID 20860828, 2010). "Despite these hints, we did not observe significant changes in ezrin/VIL2 or dematin/EPB49 mRNA expression in prostate cancer compared to benign tissues." (PMID 20860828, 2010).
hepatocellular carcinoma (21 papers, 2012 to 2025). A malignant tumor that arises from hepatocytes. "An analysis of hepatitis B-related hepatocellular carcinoma showed that ezrin overexpression was independently associated with poor differentiation and invasion, which is consistent with our results." (PMID 23209815, 2012). "Our previous study showed that the hyperphosphorylation of the ACAP4-binding protein ezrin was closely correlated to an invasive phenotype of clinical hepatocellular carcinomas (HCC) and poor survival in mice with HCC tumor xenografts." (PMID 40082743, 2025). "Our previous studies reveal that ezrin Thr567 phosphorylation plays an important role in the regulation of tumor metastasis in hepatocellular carcinoma and cellular polarity in polarized gastric cells." (PMID 32647287, 2020). "In this study we found that the inhibitory effect on hepatoma cell migration was taken through ROCK2-ezrin pathway." (PMID 32647287, 2020). "To pinpoint the inhibition of celastrol, we treated the hepatocellular carcinoma cells in a concentration gradient to evaluate the ezrin phosphorylation." (PMID 32647287, 2020). "Alternatively, the T567-phosphorylated form of ezrin can suppress Hippo signalling, as seen in hepatocellular carcinoma." (PMID 33066583, 2020). "Our findings suggest that targeting ROCK2-ezrin signaling is a potential therapeutic niche for celastrol-based intervention of cancer progression in hepatocellular carcinoma." (PMID 32647287, 2020). "In hepatocellular carcinoma cells, activation of ezrin is essential for cell migration and intrahepatic metastasis." (PMID 32647287, 2020). "KCNQ1OT1 has been shown to mediate the growth of hepatocellular carcinoma by functioning as a ceRNA of miR-504 and also to regulate proliferation and cisplatin resistance in tongue cancer via miR-211-5p-mediated Ezrin/Fak/Src signaling." (PMID 31164794, 2019). "It is also important to note that ezrin hyperphosphorylation was found to correlate with invasiveness of HCC (hepatocellular carcinoma), and inhibition of ROCK activity reduced ezrin phosphorylation and resulted in a blockade to HCC cell invasion." (PMID 24364877, 2013). "Another report revealed that pseudopod formation was clearly decreased by ezrin RNAi treatment in four hepatocellular carcinoma cell lines." (PMID 23357878, 2013). "This experiment further confirmed our hypothesis, which celastrol inhibits hepatoma cell migration via ROCK2-ezrin pathway." (PMID 32647287, 2020). "We simultaneously demonstrated that increased expression of ARHGEF10L stimulates hepatocellular tumorigenesis by activating the RhoA-ROCK1 (Rho-associated coiled-coil kinase-1)-phospho-ERM (phospho-Ezrin/Radixin/Moesin pathway) and EMT (epithelial-mesenchymal transition) in hepatocellular carcinoma." (PMID 32565805, 2020). "According to the fact that ROCK2 serves as the potential target of celastrol, we next examined whether celastrol could inhibit the ROCK2 mediated ezrin Thr567 phosphorylation in hepatocellular carcinoma cells." (PMID 32647287, 2020). "CLIC5, Ezrin, and podocalyxin were overexpressed in hepatocellular carcinoma (HCC) and the inhibition of CLIC5 and podocalyxin resulted in decreased migration and invasion." (PMID 37371090, 2023). "Studies show that the interactions of PODXL with ezrin and CLIC5 are associated with invasiveness and migration of Huh7 hepatocellular carcinoma (HCC) cell lines." (PMID 34201212, 2021). "As ROCK2 and ezrin are compartmentalized in cells and accessibility of the celastrol to its target and dephosphorylation of pre-phosphorylated ezrin could be the time-limited factor, we then treated the hepatocellular carcinoma cells with 500 nM celastrol in time gradient." (PMID 32647287, 2020).
hepatocellular carcinoma (continued). "Recent findings showed that elevated cholesterol levels promote the lipid raft localization of CD44 in a palmitoylation-dependent manner, disrupting CD44-Ezrin interactions, and ultimately decreasing the migration and metastasis of hepatocellular carcinoma (HCC) cells." (PMID 40681504, 2025). "In a line with our ezrin Thr567 phosphorylation inhibition results, celastrol inhibits the phosphorylation of ROCK2, and therefore perturbs its kinase activity in hepatocellular carcinoma cells." (PMID 32647287, 2020). "In this study, we examined the expression of EZR, CLIC5 and PODXL at the mRNA and protein levels in a modified hepatocyte resistant model (MHRM) and in cases of human hepatocellular carcinoma (HCC)." (PMID 26135398, 2015). "We demonstrate that antibody engagement of CD81 promotes hepatoma spread, which is limited by HCV infection, in an actin-dependent manner and identify an essential role for the C-terminal interaction with Ezrin-Radixin-Moesin (ERM) proteins in this process." (PMID 24662676, 2014). "In addition, the binding of celastrol to ROCK2 inhibits the migration of hepatocellular carcinoma, mainly through the impaired ROCK2-mediated phosphorylation of ezrin, resulting in ineffective ezrin activation." (PMID 36355541, 2022). "Aside from ezrin itself being important for migration and metastasis, ezrin can modulate the levels and localisation of YAP in skin fibroblasts, as well as pancreatic and hepatocellular carcinoma cancer cells." (PMID 33066583, 2020). "Together with our previous ROCK-ezrin signaling regulates the intrahepatic cancer metastasis, we identified a novel chemical drug, celastrol, which could target the ROCK2-ezrin signaling as a potential therapeutic drug to prevent the hepatocellular carcinoma metastasis." (PMID 32647287, 2020).
melanoma (20 papers, 2010 to 2026). A malignant, usually aggressive tumor composed of atypical, neoplastic melanocytes. "We also detected an increased ezrin expression in vemurafenib-resistant melanoma cells harbouring the BRAFV600E mutation." (PMID 37629086, 2023). "We have specifically found increased levels of ezrin in vemurafenib-resistant melanoma cells carrying the BRAFV600E mutation under baseline conditions and in the presence of low concentration of vemurafenib (0.8 μM)." (PMID 37629086, 2023). "Patients with high Ezrin expression in their primary melanoma had obvious poorer overall survival, with a dramatic loss of life early in the F/U period." (PMID 36142656, 2022). "Ezrin has also been implicated in the metastasis of breast cancer, pancreatic adenocarcinoma, osterosarcoma, melanoma and prostate cancer." (PMID 20856924, 2010). "Interestingly, we also detected increased ezrin expression in vemurafenib-resistant melanoma cells harbouring the BRAFV600E mutation." (PMID 37629086, 2023). "In addition, patients with high Ezrin expression in their primary melanoma had a dramatic loss of life early in their F/U period (mean survival time 29 months; range 15–44 month)." (PMID 36142656, 2022). "Indeed, we have shown that ezrin overexpression is associated with vemurafenib-resistant phenotype in BRAFV600E-mutated colon cancer and melanoma cells and that pharmacological inhibition of ezrin restores the sensitivity of resistant cells to vemurafenib in vitro." (PMID 37629086, 2023). "Moreover, caveolin-1 is associated with ezrin in highly metastatic melanoma cells." (PMID 34685548, 2021). "Collectively, our study has revealed that ezrin is commonly involved in vemurafenib resistance in BRAFV600E-mutated colon cancer and melanoma cells." (PMID 37629086, 2023). "In vitro observation of the involvement of ezrin in vemurafenib resistance in BRAFV600E-mutated RKO colon cancer cells prompted us to examine whether ezrin plays an important role in acquired resistance to BRAFV600E inhibition in another BRAFV600E-mutated cancer such as melanoma." (PMID 37629086, 2023). "It was interesting to note that the combination treatment with the ezrin inhibitor and vemurafenib induced different modes of cytostatic effects by exerting synergistic effect in melanoma vs. additive effect in colon cancer cells." (PMID 37629086, 2023). "Incorporating an Ezrin deletion mutant resulted in a significantly reduced percentage of melanoma cells engulfing live lymphocytes." (PMID 37371090, 2023). "In melanoma, aberrant HGF/Met signaling can promote melanoma metastasis by enhancing Ezrin expression via the Sp1 transcription factor." (PMID 37371090, 2023). "Early blood vessel invasion and dissemination is obvious in patients with high Ezrin expression in their primary melanomas." (PMID 36142656, 2022). "In previous studies, we reported the importance of Ezrin for melanoma cell polarization plasticity, a process important for cell migration and EMT." (PMID 36142656, 2022). "MCAM-mediated activation of PI4K signalling was reported to help recruitment of actin-linking ezrin–radixin–moesin to cell protrusions and promote melanoma cell motility." (PMID 36291660, 2022). "These phagocytic properties of melanoma cells depend on ezrin and actin recruitment; moreover, the dispersion of the actin cytoskeleton by cytochalasins abolished this process." (PMID 34685548, 2021). "These molecules inhibit the separation of the membrane from the cortex and the inflation of blebs, as shown, for example, in melanoma cells; here, high levels of the membrane-cytoskeleton linker ezrin at the uropode inhibits blebbing at the rear of the cells." (PMID 33106478, 2020). "Round blebbing melanoma cells have a uropod like region, which is rich in the linker protein ezrin and where blebbing is significantly reduced, suggesting that ezrin hinders membrane detachment." (PMID 28751725, 2017).
melanoma (continued). "These same drugs were also able to increase Ezrin expression and enhance the metastatic potential of human melanoma A375 cells, while inhibiting cell growth." (PMID 20856924, 2010). "Ezrin and L1CAM were found to interact during EMT and are important prognostic melanoma markers associated with hypoxia, which can affect EMT and may be responsible for early metastatic dissemination." (PMID 37371090, 2023). "Importantly, ezrin inhibition potentiated anti-proliferative and pro-apoptotic effects of vemurafenib in the resistant melanoma cells in a synergistic manner." (PMID 37629086, 2023). "We found just one study analyzing Ezrin expression in melanoma patients." (PMID 36142656, 2022). "It was also reported that HGF/Met signaling activates the transcriptional factor specificity protein 1 (Sp1) through the MAPK pathway, and that activated Sp1 can in turn directly bind to the promotor of the ezrin gene and regulate its transcription in melanomas." (PMID 35328667, 2022). "Ezrin expression is significantly higher in cutaneous melanomas than in benign naevi and slightly higher expression levels are observed in metastatic than in primary melanomas." (PMID 31039200, 2019). "Furthermore, ezrin expression was found to be correlated with metastasis, tumor thickness, progression, and invasion in primary melanomas of the skin." (PMID 25580109, 2014). "We observed a marked trend towards increased expression of total ezrin and phospho-ezrin in resistant melanoma cells under baseline conditions, which indicates that increased abundance of ezrin could be potentially linked with the vemurafenib-resistant phenotype in BRAFV600E-mutated melanoma cells." (PMID 37629086, 2023). "Importantly, the combination of ezrin inhibitor NSC305787 and vemurafenib at low sub-toxic concentrations exerted synergistic growth-inhibitory and apoptosis-inducing effects in resistant cells, which indicates the role of ezrin in regulating vemurafenib resistance in BRAFV600E mutant melanoma." (PMID 37629086, 2023). "However, Marshall and colleagues revealed the presence of a rigid, ezrin-enriched uropod at the rear of amoeboid, invasive A375 melanoma cells; the presence of the rearward ROCK-dependent uropod inhibited proximal bleb formation, essentially establishing rear polarity through bleb inhibition." (PMID 23024796, 2012). "We next evaluated the ability of ezrin inhibitor NSC305787 to increase anti-proliferative and anti-survival effects of vemurafenib in A375 melanoma cells with acquired resistance to vemurafenib." (PMID 37629086, 2023). "Furthermore, the treatment of ERMs with cytochalasin B was shown to remarkably suppress the metastasis and phagocytic activity of melanoma cells, indicating that the inhibition of actin assembly by ezrin inhibitors may be a potential therapeutic tool for melanoma." (PMID 36355541, 2022). "Our results highlight the relevance of Ezrin, L1CAM and HIF-1α as prognostic markers in melanoma patients." (PMID 36142656, 2022). "The fact that ezrin expression did not correlate with sentinel node positivity or outcome is not totally surprising, as most previous studies have linked ezrin expression to melanoma evolution, e. g. by demonstrating increased melanoma expression in metastases as compared with the primary tumor." (PMID 31039200, 2019). "In an effort to determine the exact molecular mechanism of CD146-stimulated migration of human melanoma cells, a recent study found that CD146 physically interacts with phosphorylated ezrin–radixin–moesin (p-ERM) proteins and recruits ERM proteins and the actin cytoskeleton to cell protrusions." (PMID 25685061, 2015). "Ezrin polarisation was also confirmed in single, disseminated melanoma or non-SCLC cells in lymph node specimens of patients and even observed in single, round melanoma cells within the tumour mass of established primary and metastatic melanomas, however, at a very low frequency (<0.1%)." (PMID 29491397, 2018).
melanoma (continued). "In addition, with the exception of PAR1 and PAFR, moesin, but not ezrin, was also necessary for the metastasis of melanoma to the lungs; this protein, both physically interacts with and was recruited by CD146." (PMID 25685061, 2015).